ITGA3 (integrin subunit alpha 3)
Diseases named in the same sentence as ITGA3 in open-access papers (continued):
Sharing a sentence is not in itself a finding about the gene and the disease.
tumor (continued). "Our previous studies showed that certain integrins are controlled directly by tumor-suppressive miRNAs (e.g., miR-29-family, miR-150, and miR-199a) and that the activation of signaling mediated by ITGA3/ITGB1 and ITGA6 enhances the aggressiveness of HNSCC." (PMID 34576110, 2021). "As expected, integrins interacting with ECM components are expressed in a cell‐type‐selective fashion, such as ITGA4, ITGAL and ITGB7 by immune cells, while tumour and stromal cells strongly expressed ITGA3, ITGAV and ITGB1/4/5/6/8." (PMID 34841720, 2021). "In line with previous research, we found that ITGA3 expression in SKCM tissues was significantly increased (in comparison with non-tumor tissue)." (PMID 34660316, 2021). "Because the deletion of Itga3 in HB SCs had a larger effect on the initiation of tumorigenesis than on the rate of tumor growth, we investigated a potential role of α3β1 in establishing a tumor-supportive environment." (PMID 32423907, 2020). "Tumor progression was more commonly observed in K19 Itga3 KO (five of seven) than in K19 Itga3 WT mice (three of seven)." (PMID 32423907, 2020). "In line with this, K19 Itga3 KO mice exhibited significantly lower tumor burden than WT mice (K19 Itga3 KO 1313.5 and WT 2296.1 mm2 on average)." (PMID 32423907, 2020). "We observed a decreasing expression level of HSPB8 and PRKN and an increasing expression level of EGFR, CDKN2A, FADD, and ITGA3 in tumor samples." (PMID 33456497, 2020). "Our recent study of PDAC revealed that the tumor-suppressive miR-124-3p directly regulates ITGA3 and ITGB1 expression, and aberrant expressions of these integrins were closely involved in PDAC molecular pathogenesis." (PMID 32899691, 2020). "Despite the similar tumor onset in both groups, the survival of Itga3 KO mice was reduced compared to the WT group." (PMID 31101121, 2019). "The downstream signaling of HER2 that drives the formation and progression of tumors therefore appears to be independent of α3β1, enabling normal tumor onset and initial tumor development in Itga3 KO mice." (PMID 31101121, 2019). "The FOXE1 and ITGA3 expression and protein levels were negatively associated with miR‐524‐5p expression in PTC cell lines, patients' tumor and papa‐cancer tissues." (PMID 30941771, 2019). "Another gene named ITGA3 has been widely reported to function as a cell surface adhesion molecule and is involved in the malignant metastasis of certain tumor subtypes." (PMID 30205473, 2018). "We found that the expression of ITGA3 was higher in tumor tissues than in paired peritumor tissues of the 46-patient cohort." (PMID 29511671, 2018). "Immunohistochemistry assays were performed to analyze ITGA3 expression in paired tumor tissue slides and peritumor tissue slides obtained from 46 ICC patients from 2013 to 2015." (PMID 29511671, 2018). "To investigate the clinical significance of ITGA3, ITGA6, and TNC in HNSCC, we analysed their associations with tumor stage and lymph node stage using the TCGA-PRAD database." (PMID 28415821, 2017). "This investigation intended to evaluate the association between FN-1, ITGA-3, ITGB-5, MMP-2, and MMP-9 gene and protein expression levels in tumor tissue with clinical and histopathological neoplastic parameters of cancer dissemination." (PMID 24737953, 2014). "Importantly, ​​high expression levels of ITGA3/5/6 correlate with advanced tumor stage, lymph node metastasis, and poor patient survival​​, suggesting their potential as ​​prognostic biomarkers​​ and ​​therapeutic targets​​." (PMID 41602372, 2026). "Given that ITGA3 levels remain primarily unaffected by tumor progression, it could serve as a dependable biomarker for prognosis, particularly within specific BC subtypes, such as ER-positive, Luminal A, and Luminal B subtypes." (PMID 40181838, 2025).
tumor (continued). "Notably, the mRNA and protein expression of ITGA3 shows minimal variation across different cancer stages or nodal metastasis statuses, indicating stable expression throughout tumor progression, including tumor growth and metastasis." (PMID 40181838, 2025). "In Luminal A and B subtypes, high ITGA3 expression may reflect a less aggressive tumor phenotype, possibly by enhancing cell adhesion to the extracellular matrix, thereby inhibiting metastatic processes." (PMID 40181838, 2025). "Integrin subunit alpha 3 (ITGA3) is a cell surface adhesion protein involved in tumor progression." (PMID 40630951, 2025). "While the signal differences of the WFL assays between normal and tumor tissues were relatively low as compared to other lectin assays, suggesting only minor changes in GalNAc structures of these six ITGs, the ITGA3–WFL assay resulted in high discrimination between tumor and normal tissues." (PMID 40287842, 2025). "In the model, ITGA3 and TNFSF10 were identified as risk factors, with high expression adversely affecting the prognosis of PC patients, while CDK11A and RHOG were protective factors, with high expression being favorable for tumor prognosis." (PMID 38956290, 2024). "Additionally, scRNA-seq analysis revealed higher ITGA3 expression in tumor cells compared with normal hepatocytes." (PMID 39085893, 2024). "We next examined the role of ITGA3 on tumorigenesis and tumor cell invasiveness in vivo." (PMID 38319712, 2024). "Finally, wound healing and transwell assays were conducted to elucidate the role of ITGA3 in tumor metastasis." (PMID 39085893, 2024). "Here, we performed a comprehensive bioinformatics analysis of multiple datasets derived from CRC patients and showed that elevated expression of NID1 and the genes ITGA3, ITGB1, and ITGAV, which encode NID1 receptors, is associated with poor prognosis and advanced tumor stage." (PMID 38001576, 2023). "Notably, we showed that ITGA3 expression was elevated in PCa tumor tissues compared with controls in eight microarray datasets and the TCGA PAAD cohort." (PMID 36561844, 2022). "Moreover, highly expressed ITGA3 was proved to stimulate the proliferation and metastasis of tumor cells in former studies." (PMID 34938358, 2021). "Firstly, we explored the expression of ITGA3 in different tumor stages." (PMID 35174063, 2021). "The up-regulated genes such as DSG3 and LGR5 might facilitate tumor metastasis, while the downregulation of ITGA3 changed the extracellular matrix and might promote tumor expansion." (PMID 34222020, 2021). "Further study of ITGA3 is needed, but discrepancies may be attributed to unique cellular contexts and tumour microenvironments." (PMID 34943783, 2021). "Although both K19 Itga3 KO and WT mice developed numerous tumors by the end of the treatment (K19 Itga3 KO 33.8 and WT 49.1 tumors on average), there was a marked 30% decrease in tumor formation and a 15% decrease in the average tumor size upon the deletion of Itga3 in HB SCs." (PMID 32423907, 2020). "This could explain the differences in tumor volume, yet similar cell proliferation and apoptosis of the analyzed Itga3 KO and WT tumors at the time of sacrifice." (PMID 31101121, 2019). "Moreover, we found ITGA3 expression correlated with several clinicopathological features, including tumor size, lymph node metastasis, and the TNM stage." (PMID 29511671, 2018). "Furthermore, the expression levels of tumor invasion-associated genes (MMP17 and ITGA3) were enriched in organoids (and tumor)." (PMID 30353124, 2018). "Furthermore, we examined the correlation between ITGA3 expression and tumor size." (PMID 40181838, 2025). "ITGA3 was associated with ER status but not age, tumor, node, metastasis stages, or tumor size." (PMID 40181838, 2025). "Notably, multivariate analysis revealed that PLAU protein upregulation in association with ITGA3, and PPP1R14B expression, tumour stage, and smoking history could predict poor overall survival in PDAC." (PMID 36591282, 2022).
tumor (continued). "We further found that ITGA3 was negatively correlated with monocyte markers (CD86), TAM markers (CCL2 and IL10), and M2 macrophage markers (CD163 and MS4A4A), suggesting that ITGA3 could regulate the polarization of TAMs and promote tumor growth and metastasis." (PMID 34094951, 2021). "We found ITGA3 significantly associated with primary therapy outcome (p < 0.0001), ITGA6 significantly associated with OS status (p = 0.026), ITGB4 significantly associated with cancer status (p = 0.042) and tumor residual (p = 0.024), ITGB8 significantly associated with chemotherapy (p = 0.020)." (PMID 32765584, 2020). "Thus, the PTC tumor cell viability was controlled by miR‐524‐5p, ITGA3, and FOXE1." (PMID 30941771, 2019). "Mechanistically, ITGA3 promotes epithelial-mesenchymal transition (EMT), enhances matrix metalloproteinase expression, and facilitates tumor cell detachment, thereby initiating CTCs formation." (PMID 41881953, 2026). "Analysis indicates that ITGA3, ITGA5, and ITGA6 have activating or inhibiting effects on multiple tumor-related pathways." (PMID 41602372, 2026). "The largest mean differences between tumor and normal tissues were observed in UEA assays ITGA2–UEA, ITGA3–UEA, and ITGB1–UEA." (PMID 40287842, 2025). "The largest S/B ratios between tumor and normal tissues were observed in ITGA5–SBA, ITGA5–MAA, ITGA3–UEA, and ITGB1–SBA, each demonstrating a large overlap between normal and tumor tissues." (PMID 40287842, 2025). "In this study, we assessed the correlation of ITGA3 expression with different clinical factors such as age, TNM stage, tumor size, and ER status." (PMID 40181838, 2025). "Expression of ITGA3 mRNA in PTC tissues was evaluated in the TIMER 2.0 database, and revealed higher expression in multiple tumours, including PTC, than the normal controls." (PMID 40138447, 2025). "We observed significantly higher expression of METTL16, ITPR1, CAPN2, ITGA3, RAC1, ITGA6, and CHMP28 in tumor samples (P<0.05)." (PMID 39434688, 2024). "Among stromal fibroblast cells, ITGAV, ITGA1, ITGB1, and ITGB5 were significantly upregulated following IO and, notably, isolated tumor cells found in the stroma showed upregulation of B2M, VIM, ITGA5, ITGB2, and ITGA3." (PMID 39639369, 2024). "Homotrimeric collagen I increases proliferation of tumor cells through DDR1 and signaling through ITGA3 compared to heterotrimeric collagen I." (PMID 38659022, 2024). "Through RNA-Seq analysis of HNSCC samples (3 tumors and 3 para-carcinoma tissues), we identified 8 pivotal marker genes (PCDH7, CDH2, ITGA3, SEMA7A, TMEM132A, CD276, TMEM2, GPR158) that were overexpressed in tumor specimens." (PMID 38548747, 2024). "In conclusion, ZIP4 can promote EMT and induce tumor invasion and metastasis through ZEB1 and ITGA3." (PMID 39664563, 2024). "Mechanistically, LINC-PINT interacts with PRC2 at a few tumor-invasion-related gene loci, such as Early Growth Response 1 (EGR1) and Integrin alpha 3 (ITGA3), and induces their silencing, ultimately repressing cancer cell migration." (PMID 36750826, 2023). "In single-cell sequencing analysis, ITGA2, ITGA3, ADAM9, and BHLHE40 were all highly expressed in malignant ductal cells, suggesting important roles in tumor progression." (PMID 37377917, 2023). "From this study, proteins of interest identified by tandem MS-MS that were decreased in sera from tumor-bearing rats treated with OKN-007, compared to untreated, included ABCA2, ATP5B, CNTN2, ITGA3, KMT2D, MYCBP2, NOTCH3, and VCAN." (PMID 35053843, 2022). "Proteins of interest identified by tandem MS-MS that were decreased in sera from tumor-bearing rats that were either OKN-007-treated or untreated included ABCA2, ATP5B, CNTN2, ITGA3, KMT2D, MYCBP2, NOTCH3, and VCAN." (PMID 35053843, 2022).
tumor (continued). "Multivariate Cox regression analysis demonstrated that three prognostic proteins (PLAU, ITGA3, and PPP1R14B expression) and two clinicopathological factors (tumour stage and tobacco smoking history) were significantly associated with poor survival." (PMID 36591282, 2022). "These cells highly expressed the integrin family genes associated with the cell adhesion molecule pathway in contrast to epithelial tumor cells, such as ITGA2, ITGA3, ITGA5, ITGA6, and ITGAV, which were among the top-ranking DEGs." (PMID 36553542, 2022). "In this work, the data mining of PDAC scRNA-seq data revealed that ITGA2, ITGA3, ITGB4, and ITGB6 were dominantly expressed in tumor cells." (PMID 35719923, 2022). "Key TGFB activators include integrin proteins, 4 of which (ITGA2, ITGA3, ITGB1, ITGB3) displayed increased expression in the HCC tumor cells (Log2 fold change = −6.16, −5.56, −2.32, and −4.35, respectively)." (PMID 33995488, 2021). "Results showed that ITGAV (10/10), ITGA2 (7/10), ITGA3 (8/9), ITGA4 (7/10), ITGA6 (7/8), and ITGA11 (7/9) protein levels were increased in tumour tissues compared with adjacent tissues." (PMID 34709754, 2021). "For five additional candidate targets including ITGA3 (n = 11), PCDH7 (n = 6), SLC39A10 (n = 6), ATP2B2 (n = 5), and HTR2B (n = 5), a quasi H − score ≥ 150 in at least 5 tumor types was also found." (PMID 33490264, 2021). "We next verified the protein levels of the integrin α‐subunits suggested to be differentially represented between samples at the mRNA level, including ITGA2, ITGA3, ITGA4, ITGA6, ITGA11, and ITGAV using 10 paired (tumour and adjacent) ESCC patient tissues." (PMID 34709754, 2021). "Results illustrated that ITGA2, ITGA3, ITGA4, ITGA6, ITGA11, and ITGAV transcripts were increased in ESCC tumour tissues (n = 95) compared with normal tissues (n = 11)." (PMID 34709754, 2021). "2.8% of tumors, isolated from the K19 Itga3 KO mice and 8.2% of the K19 Itga3 WT tumors contained patches of GFP-positive cells, accounting to up to 5% of the total tumor area." (PMID 32423907, 2020). "Taken together, tumor-suppressive miRNAs controls the expression of ITGA2/ITGB1 and ITGA3/ITGB1 in PDAC cells, and the aberrant expressions of these integrins can play pivotal roles in the malignant features of PDAC." (PMID 32899691, 2020). "In our study, we discovered that aberrant high expression of ITGA3 correlated with proliferation and poor prognosis in ICC patients, indicating that ITGA3 overexpression accelerates tumor progression in ICC." (PMID 29511671, 2018). "We discovered that aberrant overexpression of ITGA3 in ICC patients is related to some malignant clinicopathological characteristics, such as gross tumor size, lymph node metastasis, and TNM stage." (PMID 29511671, 2018). "Our present data showed that both ITGA3 and ITGB1 were directly regulated by anti-tumor miR-124-3p in PDAC cells, and knockdown of these genes or ectopic expression of miR-124-3p significantly blocked cancer cell aggressiveness." (PMID 29988949, 2018). "This research is the first reported demonstration that ITGA3 is overexpressed and functions as an oncogene in the proliferation and cell cycle of ICC cell lines, which correlated with tumor progression in ICC patients." (PMID 29511671, 2018). "Significant differences in GS were identified in relation to the expression profiles of ITGAV1, ITGA3, ITGA6, SPARC, MMP9, and MMP16, markers that were detected in the tumour samples examined." (PMID 26674523, 2015). "In the Cox proportional hazards model of LNM, high-ITGA3/CD9, YK4, and the major width of the tumor (size) were reported as independently significant variables." (PMID 24006899, 2013). "Research has found that after ITGA3 binds to extracellular matrix components, it can trigger the phosphorylation of FAK, thereby activating downstream signaling molecules and promoting the proliferation of tumor cells." (PMID 41602372, 2026).
tumor (continued). "Quantitative reverse transcription polymerase chain reaction (qRT-PCR) revealed that ITGA3 expression was significantly upregulated in tumor tissues compared to adjacent non-tumor tissues (p < 0.001)." (PMID 41011230, 2025). "Notably, the integrin and neural-signal-related receptors, such as ITGB1, ITGA3, and ITGA5, are bound to numerous ligands between tumor regions and normal regions, suggesting its critical impact on tumor invasion." (PMID 41147013, 2025). "To further validate the biological relevance of ITGA3 in clinical HCC, we analyzed ITGA3 expression in paired tumor and non-tumor mucosa specimens (n = 83)." (PMID 41011230, 2025). "For retained introns (RI), the deletion of TSSC4 resulted in a significant decrease in the IncLevels of several tumor-regulatory genes, such as ITGA3 (decreased by 0.284), RBM39 (decreased by 0.164) and NONO (decreased by 0.125)." (PMID 39697342, 2024). "The analysis suggested that TECs might promote tumor growth and progression through the interaction of COL4A1/COL4A2 with their partner receptors (ITGAV + ITGB8 and ITGA3 + ITGB1) on epithelial cells." (PMID 39093451, 2024). "The differences in ITGA3 expression levels between tumor and non-tumor tissues were compared using the Mann–Whitney U test." (PMID 36561844, 2022). "Cell adhesion molecules such as ITGA3, CD47, MDK, ITGB1, CD55, and CDH1 show a trend of upregulation with pseudotime, indicating that cell-cell communications play an important role during the evolutionary process of tumor growth and progression." (PMID 35087839, 2021). "ITGA3 is as an integrin receptor that can promote the remodeling of the ECM, and changes in the ECM can stimulate integrin signaling to regulate the growth of tumor cells." (PMID 34094951, 2021). "Expression of ITGA3 and ITGB1 was directly regulated by tumor-suppressive miR-124-3p." (PMID 34199886, 2021). "Notably, ITGA3 and ITGB1 expression was directly regulated by tumor-suppressive miR-124-3p in PDAC cells." (PMID 32977589, 2020). "Of these, integrin α3 (also known as ITGA3, CD49c, and VLA-3 subunit alpha) is a 140 KDa protein thought to be involved in the hepatocyte growth factor (HGF)/c-Met signal pathway contributing to tumour progression." (PMID 31953437, 2020). "In more detail, SIGLEC17P expression could be used by Tregs to circulate among all tissues; CD33, PCDH1, JAM2, CDHR3, and ITGA3 would orchestrate migration/retention in NI TDLNs; CADM1 in I TDLNS; and CEACAM6 in tumor." (PMID 32601304, 2020). "In summary, NRG1, ITGA3 and MAP1LC3A may serve as tumor inducers by regulating autophagy and apoptosis in GBM." (PMID 31844032, 2019). "Several tumor-related genes such as ERO1L, ITGA3, and MAPK8 were found closest to LOXL2-e13." (PMID 25254241, 2014). "The [high-ITGA3/CD9 and YK4]-positive cases consistently exhibited a higher rate of LNM (around 80%) irrespective of the size strata, but the negative cases revealed an increasing rate of LNM with larger tumor size (>30 mm)." (PMID 24006899, 2013). "This stability suggests that ITGA3 may not directly contribute to the dynamic processes involved in tumor enlargement and spread." (PMID 40181838, 2025). "Advanced PCa cells express high levels of Integrin α3, α6, and β1 (ITGA3/A6/B1), EphA2, and connexins (Cx) such as Cx43/45 at their surface, and also increase levels of extracellular matrix (ECM) components including fibronectin (FN), osteopontin (OPN), and hyaluronan in tumor stroma." (PMID 33413659, 2021). "Some of these proteins are key components of cell-cell or cell-matrix adhesion and includes annexin and integrins such as ANXA1, ANAX2, ITGB1, ITGA3, FN1, CTNNB1, APOH which interplay may activate exosome and leukocyte adhesion to tumor cells to limit tumor growth." (PMID 30111323, 2018).